HNRNPH1 (heterogeneous nuclear ribonucleoprotein H1)
Description:
This protein is a component of the heterogeneous nuclear ribonucleoprotein (hnRNP) complexes which provide the substrate for the processing events that pre-mRNAs undergo before becoming functional, translatable mRNAs in the cytoplasm. Mediates pre-mRNA alternative splicing regulation. Inhibits, together with CUGBP1, insulin receptor (IR) pre-mRNA exon 11 inclusion in myoblast. Binds to the IR RNA. Binds poly(RG).
Synonyms: HNRPH; HNRPH1; hnRNPH; NEDCDS
Tractability: PROTAC: UniProt records ubiquitination sites on it; ubiquitination databases record sites on it; its protein half-life has been measured.
Target class: Other nuclear protein
Gene: Protein-coding gene on chromosome 5 (179,614,170 to 179,634,784, reverse strand). Ensembl gene ENSG00000169045.
Subcellular location: Nucleus, nucleoplasm
Subcellular location (Human Protein Atlas): Nucleoplasm
Pathways (Reactome):
Metabolism of RNA: Processing of Capped Intron-Containing Pre-mRNA; mRNA Polyadenylation; mRNA Splicing - Major Pathway
Disease: Dengue Virus-Host Interactions
Signal Transduction: FGFR2 alternative splicing
Gene Ontology:
Molecular function: identical protein binding; protein binding; RNA binding; poly(U) RNA binding; nucleic acid binding
Biological process: regulation of RNA splicing; mRNA splicing, via spliceosome; RNA processing
Cellular component: catalytic step 2 spliceosome; membrane; nucleoplasm; nucleus; cytosol; ribonucleoprotein complex
Genetic constraint (gnomAD): Loss-of-function variants: 2 observed, 55.57 expected, observed/expected ratio (o/e) 0.036, 90% interval 0.014 to 0.11. The upper end of that interval is the gene's LOEUF score, 0.11, which puts it in group 1 of 6, group 1 being the genes least tolerant of losing a copy. Missense variants: 248 observed, 561.99 expected, observed/expected ratio (o/e) 0.44, 90% interval 0.4 to 0.49. Synonymous variants: 183 observed, 189.77 expected, observed/expected ratio (o/e) 0.96, 90% interval 0.85 to 1.09.
Gene-disease validity (ClinGen):
ClinGen rates the evidence that HNRNPH1 causes each of these diseases.
syndromic intellectual disability (autosomal dominant): Definitive. A intellectual disability that is part of a larger syndrome.
Homologues: Orthologues: rat Hnrnph2 (99% identical), macaque HNRNPH1 (97% identical), dog HNRNPH1 (97% identical), rabbit HNRNPH1 (97% identical), mouse Hnrnph1 (97% identical), pig HNRNPH1 (88% identical). Paralogues in human: HNRNPH2 (96% identical), HNRNPF (71% identical), HNRNPH3 (49% identical), GRSF1 (34% identical), ESRP1 (29% identical), ESRP2 (27% identical), RBM12B (22% identical), RBM12 (20% identical).
Diseases named in the same sentence as HNRNPH1 in open-access papers:
HNRNPH1 is named in the same sentence as 72 diseases in open-access papers, as found by Europe PMC text mining. Sharing a sentence is not in itself a finding about the gene and the disease. The quoted sentences say what the papers report.
hepatocellular carcinoma (7 papers, 2020 to 2024). A malignant tumor that arises from hepatocytes. "Recently, an isoform switch from KHKC to KHKA mediated by a c-MYC-mediated upregulation of the splicing factors HNRNPH1/2 has been shown to promote the progression of hepatocellular carcinoma in human cells." (PMID 32733884, 2020). "Recently, the mRNA of hnRNPH1 was detected in exosomes isolated from the serum of hepatocellular carcinoma (HCC), chronic hepatitis B (CHB), and liver cirrhosis (LC) patients, resulting to significantly higher levels in patients compared to control groups." (PMID 33391635, 2020). "Alternative splicing of KhkC in the liver is mediated by APOBEC1 complementation factor (A1CF), while heterogeneous nuclear ribonucleoprotein H1/2 (hnRNPH1/2) mediates a c-myc-driven switch of KHKC to the KHKA isoform in dedifferentiated hepatocellular carcinoma (HCC) cells." (PMID 37559908, 2023). "Similarly, exosomal heterogeneous nuclear ribonucleoprotein H1 (hnRNPH1) mRNA levels, which are remarkably higher in hepatocellular carcinoma (HCC) patients than in other groups, are associated with the Child-Pugh and TNM stage classification, portal vein tumor emboli and lymph node metastasis." (PMID 33396739, 2020). "detected higher levels of hnRNPH1 mRNA in vesicles from the serum of hepatocellular carcinoma patients, in a context where an aberrant expression of hnRNPH1 was reported in different solid tumours, including hepatocellular carcinomas." (PMID 33391635, 2020). "Competitive binding between HNRNPH1 and SRSF3 to PRMT5 pre-mRNA promotes PRMT5-ISO5 production and increases radiosensitivity in hepatocellular carcinoma cells." (PMID 38405130, 2024). "Additionally, serum exosomal heterogeneous nuclear ribonucleoprotein H1 (hnRNPH1) mRNA levels in hepatocellular carcinoma (HCC) patients were significantly higher than those in control groups." (PMID 35269604, 2022).
prostate carcinoma (6 papers, 2014 to 2025). A carcinoma that arises from epithelial cells of the prostate gland. "Furthermore, studies have implicated members of the HNRNPF/H RBP family, particularly HNRNPH1, in the pathogenesis of multiple cancer types, including mantle cell lymphoma, Burkitt lymphoma, prostate cancer and Ewing sarcoma (EWS)." (PMID 40766465, 2025). "In addition, HNRNPH1 transcripts negatively regulated by miR-212 were associated with the expression of AR and AR-V7 in prostate cancer cells." (PMID 30939845, 2019). "Silencing of HNRNPH1 sensitized prostate cancer cells to bicalutamide and inhibited prostate tumor growth in vivo." (PMID 30939845, 2019). "We then selected six genes (HNRNPH1, DSC2, FBXO9, MANEA, OR51E1, PRR15L) for validation by qRT-PCR that were over-expressed in prostate cancer across all datasets and showed high fold changes in our microarray." (PMID 25003216, 2014). "HNRNPH1 exhibited a clear negative correlation with MYC activation in the majority of 27 tumor types, including prostate cancer (PRAD)." (PMID 37399401, 2023).
breast cancer (5 papers, 2010 to 2022). A primary or metastatic malignant neoplasm involving the breast. "HNRNPH1 is a member of the hnRNP family and retains an intronic sequence between exons 9 and 10 in 168FARN and 4T07 mammary tumors compared to 4T1 tumors." (PMID 20700505, 2010). "SRSF3 and HNRNPH1 regulate a splicing hotspot of HER2 in breast cancer cells." (PMID 34497807, 2021). "Among all the RBPs (HNRNPU, HNRNPK, RBM5, HNRNPLL, HNRNPH1, HNRNPM, HNRNPA2B1) screened, only SRSF7 (also known as 9G8) was substantially upregulated in hypoxia-treated breast cancer cells." (PMID 34362878, 2021). "In addition, Ai-lncRNA EGOT can recruit hnRNPH1 to enhance the AS of pre-ITPR1 and form pre-ITPR1/EGOT double-stranded RNA to upregulate the expression of ITPR1, leading to the sensitivity of breast cancer cells to paclitaxel toxicity." (PMID 34750493, 2022).
chronic hepatitis B (5 papers, 2019 to 2023). "HCC patient-derived exosomal heterogeneous nuclear ribonucleoprotein H1 (hnRNPH1) was markedly higher than that in chronic hepatitis B patients and a healthy control." (PMID 30897788, 2019). "They reported the high sensitivity (85%) and specificity (76%) of exosomal hnRNPH1 mRNA in discriminating HCC patients from chronic hepatitis B and suggested it could be utilised as a tool for cancer diagnosis." (PMID 33080904, 2020). "A study containing 291 participants revealed that mRNA levels of serum exosomal heterogeneous ribonucleoprotein H1 (hnRNPH1) were significantly higher in HCC than in cirrhosis, chronic hepatitis B, and healthy controls." (PMID 37006626, 2023).
glioma (5 papers, 2021 to 2025). A benign or malignant brain and spinal cord tumor that arises from glial cells (astrocytes, oligodendrocytes, ependymal cells). "In neurological roles, hnRNPH1 impacts normal brain development, modulates methamphetamine sensitivity (associated with genetic variants), and promotes glioma development via TRF2 splicing and Akt/mTOR pathway activation." (PMID 40507967, 2025). "In gliomas, hnRNPH1 promotes tumor progression by regulating the splicing of the pseudogene PRELID1P6, leading to the activation of the Akt/mTOR signaling pathway." (PMID 40507967, 2025). "Coexpression analyses and rescue experiments confirmed the interaction between PRELID1P6 and hnRNPH1, suggesting that hnRNPH1 is a key mediator for PRELID1P6 in promoting cell proliferation in glioma." (PMID 34108621, 2021). "In the present study, we found that hnRNPH1-promoted glioma proliferation and interacted with PRELID1P6." (PMID 34108621, 2021). "Collectively, our results showed that hnRNPH1 is important for PRELID1P6-promoted glioma proliferation." (PMID 34108621, 2021). "Mechanistically, PRELID1P6 inhibits the ubiquitin-mediated degradation of hnRNPH1, thus promoting glioma cell proliferation by the Akt/mTOR signaling pathway." (PMID 34108621, 2021). "In this study, we found that the pseudogene PRELI domain-containing 1 pseudogene 6 (PRELID1P6) plays a pivotal role in glioma cell proliferation by enhancing heterogeneous nuclear ribonucleoprotein H1 (hnRNPH1) stability." (PMID 34108621, 2021). "Because hnRNPH1 is vital for PRELID1P6-promoted glioma proliferation, we also detected the phosphorylation levels of Akt/mTOR signaling pathway proteins after hnRNPH1 knockdown." (PMID 34108621, 2021). "PRELID1P6 mediates ubiquitin-mediated degradation of hnRNPH1 and promoting glioma proliferation." (PMID 36348434, 2022). "Moreover, we carried out immunoprecipitated assays in glioma cells using an anti-hnRNPH1 antibody and detected ubiquitin levels by western blotting." (PMID 34108621, 2021). "In addition, PRELID1P6 knockdown in glioma cells decreased hnRNPH1 stabilization, shortening the half-life of hnRNPH1." (PMID 34108621, 2021). "Knockdown of hnRNPH1-promoted glioma cell apoptosis, although PRELID1P6 was overexpressed." (PMID 34108621, 2021). "However, little is known about the function and mechanism of hnRNPH1 in glioma." (PMID 34108621, 2021). "In conclusion, METTL3-mediated m6A triggered mitochondrial fission by facilitating the binding between HNRNPH1 and LINC00475, thereby promoting glioma progression." (PMID 38405130, 2024). "METTL3-dependent m6A methylation enhanced the binding of GYR and GY domains of HNRNPH1 to LINC00475, ultimately promoting glioma progression by inducing mitochondrial fission." (PMID 38405130, 2024). "METTL3 facilitated HNRNPH1-mediated AS of LINC00475, which promoted glioma progression by inducing mitochondrial fission." (PMID 38405130, 2024). "Pseudogene PRELID1P6 activates Akt/mammalian (or mechanistic) target of rapamycin (mTOR) pathway by increasing HNRNPH1-mediated TRF2 splicing and promoting glioma development." (PMID 38405130, 2024). "Because we found that PRELID1P6 plays an oncogenic role in glioma and PRELID1P6 inhibited the ubiquitin-mediated degradation of hnRNPH1, we next investigated the impact of hnHNPH1 on glioma cell proliferation." (PMID 34108621, 2021).
Chronic Myeloid Leukemia (4 papers, 2021 to 2025). "Both in vivo and in vitro studies have indicated that silencing HNRNPH1 hinders cell proliferation and enhances apoptosis in Chronic Myeloid Leukemia cells." (PMID 40729372, 2025). "In other cancers, hnRNPH1 was shown to be upregulated in chronic myeloid leukemia (CML) patients and cell lines which correlated with disease progression." (PMID 37759675, 2023). "However, the function of HNRNPH1 in chronic myeloid leukemia (CML) remains unclear." (PMID 34295818, 2021).
colorectal cancer (4 papers, 2021 to 2024). A primary or metastatic malignant neoplasm that affects the colon or rectum. "Their data underline the oncogenic potential of hnRNPH1 reported in different human cancers, including colorectal carcinoma." (PMID 36611995, 2023). "The expression level of HNRNPH1 was high in normal colorectal tissues and varied from low to high expression in colorectal cancer patients." (PMID 39023715, 2024). "Our finding is furthermore in accordance with data from hnRNPH1-IP transcriptome analysis identifying caspase-7 as a putative RNA target of hnRNPH1 in the colorectal cancer cell line HCT116." (PMID 36611995, 2023). "Among these hub genes, HNRNPL and HNRNPH1 genes may be molecular markers for early colorectal cancer diagnosis in MSS.TRA2A and SRSF6 may play important roles in PCRC metastasis." (PMID 39023715, 2024). "Among them, HNRNPH1 and WAC, targeted by hsa-miR-4772-5p, have been described in previous colorectal cancer studies." (PMID 34512726, 2021).
Ewing sarcoma (4 papers, 2021 to 2025). A small round cell tumor that lacks morphologic, immunohistochemical, and electron microscopic evidence of neuroectodermal differentiation. "Taken together, these data suggest that loss of hnRNPH1 partially phenocopies the effects of MS0621 on EWSR1::FLI1-dependent phenotypes in Ewing sarcoma." (PMID 36793594, 2023). "As hnRNPH1 interacted robustly with MS1360 under all tested conditions, we hypothesized that hnRNPH1 is a core member of the MS0621-interacting complex and that loss of hnRNPH1 would recapitulate the effects of MS0621 on Ewing sarcoma cells." (PMID 36793594, 2023). "Splicing of EWS-FLI1 in Ewing sarcoma has been shown to be regulated by HNRNPH1, and HNRNPH1 plays a primarily oncogenic role in the nucleus." (PMID 34148056, 2021). "In ES (Ewing Sarcoma), hnRNPH1 regulates the splicing of the EWSR1::FLI1 fusion gene, promoting the production of oncogenic transcripts." (PMID 40507967, 2025). "Although the effect of the hnRNPH1 silencing seemed modest, EWSR1::FLI1 levels increased and Ewing sarcoma cell line proliferation was dramatically reduced." (PMID 36793594, 2023). "To test this hypothesis, we used CRISPRi-mediated silencing of hnRNPH1 and EWSR1 in Ewing sarcoma cell lines." (PMID 36793594, 2023).
acute myeloid leukemia (3 papers, 2022 to 2025). Acute myeloid leukemia (AML) is a group of neoplasms arising from precursor cells committed to the myeloid cell-line differentiation. "Elevated expression of HNRNPH1 was found in acute myeloid leukemia (AML), and knockdown of HNRNPH1 alleviated cell proliferation." (PMID 36514015, 2022). "Diagnosed with acute myeloid leukemia (AML) through morphology, immunology, Cytogenetics, and Molecular biology (MICM) typing, with a confirmed HNRNPH1-ERG fusion gene." (PMID 40193682, 2025).
amyotrophic lateral sclerosis (3 papers, 2019 to 2025). Amyotrophic lateral sclerosis (ALS) is a neurodegenerative disease characterized by progressive muscular paralysis reflecting degeneration of motor neurons in the primary motor cortex, corticospinal tracts, brainstem and spinal cord. "Additionally, hnRNPH1 has been linked to oligodendrocyte dysfunction in amyotrophic lateral sclerosis/frontotemporal lobar degeneration (ALS/FTLD) spectrum disorders, suggesting its involvement in disease processes via its effects on myelination." (PMID 40507967, 2025).
colon carcinoma (3 papers, 2022 to 2023). "Together, these data suggest that TRIM25 represents a novel caspase-7 mRNA-binding protein, which, in concert with RNA-bound hnRNPH1, promotes the constitutive decay of caspase-7 mRNA in colon carcinoma cells." (PMID 36611995, 2023). "Likewise, hnRNPH1 plays a critical role in several human malignancies, including colon cancer." (PMID 36611995, 2023).
melanoma (3 papers, 2023 to 2025). A malignant, usually aggressive tumor composed of atypical, neoplastic melanocytes. "To further investigate the correlation between hnRNPH1 and hnRNPH2 expression and melanoma, we compared their expression levels in melanoma cell lines and melanocytes from NanoString gene expression analysis." (PMID 41301529, 2025). "The results presented in this study demonstrate the impact of 2155-14, 2155-18, and hnRNPH2 siRNA in downregulating spliceosomal proteins hnRNPH1 and hnRNPH2 in melanoma cells." (PMID 41301529, 2025). "Results of nCounter analysis of hnRNPH1 and hnRNPH2 expression after siRNA treatment in melanoma cells and primary adult melanocytes." (PMID 41301529, 2025). "The results of this study offer valuable insights into pharmacologic and siRNA targeting of hnRNPH1 and H2 proteins in melanoma cells with respect to their immunomodulatory effects in melanoma." (PMID 41301529, 2025). "The results revealed that hnRNPH1 and hnRNPH2 gene expression levels were significantly lower in melanocytes compared to melanoma cell lines." (PMID 41301529, 2025). "Our results indicated that treating melanoma cell lines with 2155-14 and 2155-18 led to hnRNPH1/H2 downregulation, whereas hnRNPH2 siRNA treatment led to only hnRNPH2 downregulation." (PMID 41301529, 2025). "The present study investigated the effect of genetic and pharmacologic downregulation of hnRNPH1/H2 on melanoma immunogenicity in vitro." (PMID 41301529, 2025). "The NanoString assays revealed significantly lower gene expression levels of hnRNPH1 and hnRNPH2 in untreated melanocytes compared to untreated melanoma cell lines, consistent with our group’s previous Western blot findings." (PMID 41301529, 2025). "We previously reported melanoma actives that work via binding and downregulating spliceosomal proteins hnRNPH1 and H2." (PMID 36830718, 2023). "We previously reported anti-melanoma compounds that work by downregulating spliceosomal proteins hnRNPH1 and H2." (PMID 37759675, 2023). "Nothing is known about the role of hnRNPH1 and H2 in melanoma development and homeostasis." (PMID 37759675, 2023). "This agrees with the hypothesis that downregulation of hnRNPH1/H2 can lead to the selective death of melanoma cells as we previously posited." (PMID 37759675, 2023).
Burkitt lymphoma (2 papers, 2021 to 2022). A rare form of malignant mature B-cell non-Hodgkin lymphoma. "HNRNPH1, as a member of the hnRNP family, is associated with the methyltransferase function of PRMT5 and is involved in the tumorigenic progression of Burkitt lymphoma and HCC." (PMID 36499164, 2022). "HNRNPH1, which is localized in the nucleus, has been shown aberrantly overexpressed in hematological malignancies including AML, Burkitt lymphoma, and T-acute lymphoblastic leukemia." (PMID 34295818, 2021).
colorectal tumor (2 papers, 2022 to 2023). "Concordantly, the aberrant expression of hnRNPH1 in colorectal tumor tissue is also evident in the data from the USC Xena platform." (PMID 36611995, 2023). "We note that four genes (SAT1, MT1E, HSP90AA1, and HNRNPH1) from a colorectal tumor tissue have interactions with HIV-1 proteins." (PMID 36290397, 2022).
frontotemporal dementia (2 papers, 2019 to 2023). Frontotemporal dementia (FTD) comprises a group of neurodegenerative disorders, characterized by progressive changes in behavior, executive dysfunction and language impairment, as a result of degeneration of the medial prefrontal and frontoinsular cortices. "In addition, HNRNPH1 sequestration in RNA foci has been implicated in neurodegenerative disease models of frontotemporal dementia, associated with impaired splicing functions." (PMID 37248947, 2023).
latent infection (2 papers, 2015 to 2021). "The increase in latent infection after knockdown of TOP2A and HNRNPH1 was coupled with a decrease in productive infection." (PMID 34194479, 2021). "On the other hand, a dramatic increase in latent infection was seen after knockdown of TOP2A, SRP14, HNRNPH1, DDX1, and HNRNPL (blue bars)." (PMID 34194479, 2021).